BRAF (B-Raf proto-oncogene, serine/threonine kinase)
Diseases named in the same sentence as BRAF in open-access papers (continued):
Sharing a sentence is not in itself a finding about the gene and the disease.
melanoma (continued). "In addition, CDC42 and its downstream p21-activated kinases (PAKs) are regulators of mitogen-activated protein kinase (MAPK) inhibitor resistance in BRAF mutant melanoma." (PMID 35385746, 2022). "In a long-term KEYNOTE-006 trial follow up, BRAF-mutated melanoma patients who were not treated with a prior BRAFi lad longer PSF on pembrolizumab treatment (7.0 months) than those who were treated initially witb RAFi (2.8 months)." (PMID 35565255, 2022). "This was the case with lack of detection of BRAF G469E in one patient as this infrequent melanoma mutation (0.1% incidence) was not covered in the custom panel design." (PMID 35494035, 2022). "The incidence of BRAF gene mutations in melanoma is as high as 40–50%, but the therapeutic effect is not optimal when targeted BRAF." (PMID 35896782, 2022). "Specifically, in the CheckMate067 trial, 22% of treatment-naïve metastatic melanoma patients achieved a CR upon combined checkpoint-inhibitor therapy with ipilimumab + nivolumab with slightly better survival outcomes for BRAF-mutant melanoma patients, which showed a median PFS of 16.8 months." (PMID 35565212, 2022). "CDC42 regulates melanoma invasion and is activated in BRAF-resistant melanoma cells." (PMID 35385746, 2022). "Activation of HMOX2 by oncogenic BRAF promotes the increase of melanospheres in melanoma." (PMID 35232428, 2022). "Restoration of IFNAR1 signaling in BRAF mutant melanoma cells attenuated tumor growth in vivo." (PMID 35269844, 2022). "Host immunity is crucial for the anti-melanoma activity of BRAF and MEK inhibitors." (PMID 35847840, 2022). "Finally, using treatment of melanoma cells with a BRAF inhibitor as an example, we show that our model can be used to predict the metabolic and gene expression changes in cancer cells in response to drug treatment." (PMID 35148308, 2022). "NRF2 promotes the migration and invasion of BRAF mutant melanoma cells." (PMID 36203561, 2022). "Related to this, recent evidence shows that activation of mTORC1 drives resistance to BRAF inhibitors in melanoma and suggest that BRAF/mTORC1 combinatorial therapy may improve patient survival by reducing the probability of relapse." (PMID 35912100, 2022). "The development of targeted therapies and immunotherapies has led to significant improvement in overall survival, particularly in non-NRAS-mutated melanoma (BRAF)." (PMID 36428530, 2022). "The only case in which such a downregulation was found not significant was for miR-200c expression in BRAF mutated primary tumors in relation to melanoma-specific death." (PMID 35326682, 2022). "The MassARRAY-based OncoFOCUS panel (v3) was previously adopted in our community pathology lab as a fully validated clinical test of common mutations in BRAF, EGFR, KIT, KRAS, and NRAS genes, which are implicated in various cancers, particularly colon cancer, lung cancer and melanoma." (PMID 35446881, 2022). "Similarly, BRAF inhibitors in human A375 sensitive melanomas cells impaired glycolysis in vitro, as attested by a decreased 13C-pyruvate -13C-lactate exchange in response to vemurafenib." (PMID 35327519, 2022). "In addition, SEMA6A regulates actin cytoskeleton remodeling through RhoA-dependent activation of YAP in BRAF-mut melanoma cells." (PMID 36601121, 2022). "In this study, we have approached this hypothesis by silencing known negative regulators of the MAPK pathway and evaluating the effects of this perturbation on the survival of BRAF/NRAS-mutant melanoma cells." (PMID 35580987, 2022). "Moreover, THC treatment of mice with BRAF wild-type melanoma xenografts generated with CHL-1 melanoma cells or treatment with a combination of THC and CBD resulted in a stronger reduction in cancer growth than treatment with temozolomide." (PMID 35406541, 2022). "One prominent example is the resistance of melanoma cells to BRAF inhibitor therapy." (PMID 36401282, 2022).
melanoma (continued). "Besides, adjuvant treatment with BRAF inhibitor dabrafenib and MEK inhibitor trametinib is approved in resected stage III melanoma with BRAF V600E or V600K mutations." (PMID 36254250, 2022). "Finally, in BRAF-mut melanoma patients treated with dabrafenib+trametinib, high SEMA6A predicts shorter recurrence-free interval." (PMID 35440004, 2022). "HMGCL expression is upregulated in BRAF V600E melanoma and hairy-cell leukemia." (PMID 35681673, 2022). "Moreover, another study reported reduced tumor growth of BRAF-inhibitor-sensitive as well as BRAF-inhibitor-resistant human melanoma xenografts induced by a KD." (PMID 35851093, 2022). "Still, disruption of redox balance enhances the effects of BRAF-inhibition in melanoma." (PMID 35326089, 2022). "In addition, inhibitors of the TGFβ receptor TGFBR1 prevented the development of resistance to BRAF inhibitor vemurafenib in BRAF mutant melanoma cells." (PMID 36295658, 2022). "Mutually exclusive somatic TERT promoter mutations, C250T, C228T and CC242TT, were found in 48% (10/21) of the melanoma cohort and increased the overall ctDNA detection rate from 67%, based on detection of driver (NRAS or BRAF) or cancer-associated mutations, to 71%." (PMID 35494035, 2022). "Furthermore, the activity of SEMA6A/RhoA/YAP axis is induced by dual BRAF/MEK inhibition by dabrafenib+trametinib and, in an environmental-mimicking condition of melanoma cells and fibroblasts co-culture, is associated with reduced targeted therapy efficacy." (PMID 35440004, 2022). "Similar to melanoma, acquired activating MEK1 mutation or overexpression of HER2/3 may confer resistance to the single BRAF inhibition." (PMID 36091770, 2022). "Indeed, multiple preclinical studies in murine melanoma models examined the combination of BRAF/MEK inhibition with anti-PD-1/PD-L1 and showed promising results." (PMID 35806358, 2022). "Moreover, due to the development of drug resistance and tumor recurrence, patients with BRAF-mutant melanoma have a short response time to BRAF/MEK inhibitors." (PMID 36588679, 2022). "Therefore, high-dose ascorbate is a promising pharmacological approach to treating refractory melanomas, e.g., with secondary resistance to targeted BRAF inhibitor therapy." (PMID 35406796, 2022). "Drugs targeting BRAF mutations approved by the Food and Drug Administration agency (FDA), such as vemurafenib, have culminated in drastic improvement in the response rates and overall survival of melanoma patients." (PMID 36555289, 2022). "A subgroup analysis from CheckMate-067 demonstrated that the absolute difference in 5-year overall survival was substantially greater for the combination than nivolumab alone in patients with BRAF-mutant melanoma (60% ipilimumab plus nivolumab vs. 46% nivolumab alone)." (PMID 36016960, 2022). "We first evaluated whether SOX2 could desensitize melanoma cells to BRAF inhibition by knocking down SOX2 in A375, A2058, and SK-MEL-5 cells." (PMID 35944584, 2022). "Mutation of BRAF (50%), NRAS (25%), and neurofibromin 1 (14%) are common in melanoma." (PMID 35915735, 2022). "Therefore, only a few public institutions provide testing for melanoma patients for research purposes, and most rely on industry-sponsored BRAF testing." (PMID 36589179, 2022). "We also sought to investigate whether sGSN deficiency might benefit the response to targeted therapy with BRAF inhibitor in a mouse mutant-Braf melanoma model." (PMID 36162919, 2022). "BRAF and MAPK mutation are considered early carcinogenic events in melanoma." (PMID 35401191, 2022). "Therefore, we assessed the efficacy of BRAF/PI3K combined inhibition in inhibiting melanoma progression in the tumor stromal niche and enhancing the antitumor effect of vemurafenib." (PMID 36026581, 2022).
melanoma (continued). "Currently available cell-based models of drug-resistant melanoma are derived either from BRAF V600E melanomas that have been subjected to prolonged small molecule BRAF inhibition, or from cells overexpressing exogenous copies of the gene in question from a non-native promoter." (PMID 36358868, 2022). "Therapeutic strategies in the context of V600K BRAF-mutated melanoma are not as well elucidated as those with V600E and prognosis is poor." (PMID 35954441, 2022). "Of note, BRAF inhibitors are commonly used in, e.g., melanoma treatment." (PMID 35055192, 2022). "In a recent study, we sought to uncover novel vulnerabilities of BRAF-V600E-induced senescent cells (BRafSen cells) that could be targeted by senolytics to prevent melanoma formation." (PMID 35306485, 2022). "Esta hipótesis se basa en la observación in vitro del mayor crecimiento de células de melanoma BRAF mutado, tratadas con metformina, debido a la regulación al alza de VEGF." (PMID 35569426, 2022). "Treatment with v‐Raf murine sarcoma viral oncogene homolog B (BRAF) inhibitors and mitogen‐activated protein kinase (MEK) inhibitors can induce rapid tumor control with improved overall survival (OS) in BRAF mutant melanoma patients; however, the duration of response is often short lived." (PMID 35924450, 2022). "Examples are v-raf murine sarcoma viral oncogene homolog B (BRAF) protein inhibitors in melanoma." (PMID 36361831, 2022). "Herein, we review the current clinical data for characteristics and response to targeted therapy of melanomas lacking a V600 BRAF mutation." (PMID 35380338, 2022). "However, despite their proven efficacy, it was demonstrated that treatment of melanomas with BRAF inhibitors renders them dependent on ATP generation by the mitochondria and the association with inhibitors of oxidative phosphorylation may enhance the effect of BRAF inhibitors in melanoma patients." (PMID 36431906, 2022). "Later, in a phase III clinical study as a single agent for patients with BRAF V600E- or V600K-mutant melanoma, treatment with trametinib obtained an ORR of 22% and PFS of 4.8 months, compared to an ORR of 8% and a PFS of 1.5 months for the group treated with chemotherapy." (PMID 36358912, 2022). "As a therapeutic target for melanoma, BRAF can regulate the expression of KYNU." (PMID 35893303, 2022). "On the contrary, multiple studies have shown that mutant BRAF protein epitopes may be recognized by host immunity and induce anti-melanoma immune responses." (PMID 35565255, 2022). "Moreover, it has been reported that a high-fat ketogenic diet enhances growth of BRAF V600E melanoma cells xenotransplanted into mice and that hypolipidemic agents can constrain tumor growth." (PMID 35912092, 2022). "In general, melanomas carry a mutated NRAS, BRAF or concurrent BRAF and PTEN mutations." (PMID 36613640, 2022). "Additionally, ARN22089 has a favorable pharmacokinetic profile and can inhibit the growth of BRAF mutant mouse melanomas and patient-derived xenografts in vivo." (PMID 35385746, 2022). "Alternatively, the presence of BRAF V600E in most of the melanoma lines (8 out of 9 melanoma cell lines) may suggest that this INP may have a more general effect on growth inhibition in melanoma." (PMID 35525914, 2022). "Since anti-PD1 Abs are widely applicable to the treatment of advanced melanoma even without BRAF mutations, anti-PD1 Ab-based regimes for the treatment of advanced melanoma have recently been developing." (PMID 36555362, 2022). "We then investigated whether the endogenous level of SOX2 alters the response of melanoma cells to BRAF-targeted therapy." (PMID 35944584, 2022). "In addition, eligibility criteria were relaxed to allow enrolment of patients with pancreatic cancer, colorectal cancer, and BRAF V600E mutant melanoma who had progressed on BRAF inhibitors in the Mod and Sev cohorts." (PMID 35130943, 2022).
melanoma (continued). "Similarly, a recent study of 1764 patients with advanced melanoma from a nationwide registry confirmed the prolonged mPFS and mOS in BRAF-mutant melanoma compared with NRAS-mutant and double wild-type melanoma." (PMID 36428582, 2022). "Vemurafenib and dabrafenib are only effective in BRAF V600-mutant melanoma." (PMID 35406444, 2022). "Furthermore, soluble TNF-N induces resistance to BRAF inhibitors in melanoma cells and cisplatin chemotherapy in malignant pleural mesothelioma." (PMID 36578029, 2022). "While there are similar lipid droplet phenotypes seen in diseases harboring BRAF V600E mutations, mutations in RAS are also frequently observed in melanoma and could potentially result in similar metabolic changes." (PMID 35565240, 2022). "Furthermore, it has been observed that BRAF inhibitor treatment led to the enrichment of a small population of melanoma cells in a dedifferentiated state, termed BRAF inhibitor persister cells." (PMID 36119516, 2022). "However, its clinical efficacy is limited, and it cannot completely inhibit the recurrence of melanoma and PTC with high BRAF mutation rate." (PMID 35748101, 2022). "The movie was captured using two-color PALM live imaging of NRas and BRAF in 108T melanoma cell." (PMID 36304112, 2022). "At present, BRAF inhibitors have been widely used in the clinical treatment of melanoma." (PMID 36551302, 2022). "This was further demonstrated in a study that showed overexpressing cyclin D1 in a melanoma cell line could promote BRAF inhibitor resistance." (PMID 35525274, 2022). "In addition to the genetic variability of melanoma, resistance to BRAF inhibitors can also be generated by the microenvironment and epigenetic changes." (PMID 35565444, 2022). "While BRAF V600E is a predominant driver in some cells, especially in melanoma, other cells with this mutation are not entirely dependent on it for oncogenic proliferation." (PMID 36011019, 2022). "al included 12 patients with BRAF mutant melanoma with brain metastases who underwent radiation therapy prior to or during vemurafenib and found that two patients had developed steroid dependence due to intracranial edema and one patient experienced radiation necrosis." (PMID 36579260, 2022). "Indeed, the combination of BRAF inhibitor encorafenib and panobinostat induced caspase-dependent cell death in melanoma cell lines, including those initially resistant to BRAF inhibitors." (PMID 35409020, 2022). "The discovery of BRAFV600E activating mutations in melanoma led to the development of specific BRAFV600E inhibitors that currently, in combination with MEK inhibitors, represent the first-line of treatment for BRAF mutant melanomas." (PMID 36402789, 2022). "Thus, the possible use of SEMA6A protein assessment as predictive biomarker in BRAF-mut melanoma deserves further investigation." (PMID 35440004, 2022). "Following the introduction of CTLA4 and PD1 immune checkpoint inhibitors, the optimal sequence of targeted therapy and immunotherapy for the treatment of patients with BRAF-mut melanoma is under investigation in clinical trials (DREAMseq [NCT02224781] and SECOMBIT [NCT02631447])." (PMID 35440004, 2022). "All of BRAF V600E/K or NRAS Q61K/L/R driver mutations identified using the ArcherDX custom melanoma ctDNA panel and tissue biopsy were also identified using either ddPCR or a Thermofisher custom melanoma ctDNA panel." (PMID 35494035, 2022). "The interesting cases of patient #A10, in which ctDNA remained negative despite disease progression to iliac lymph nodes—a result which was later confirmed to be truly BRAF WT at tissue analysis—highlight a good clinical correlation that better recapitulate melanoma biology in a clinical scenario." (PMID 35804825, 2022). "However, the role of NLRP3 in melanoma is unclear as another recent report found its activity induces cell death in BRAF inhibitor-resistant melanomas and improves prognosis." (PMID 35515106, 2022).
melanoma (continued). "The high rate of BRAF mutations has led to the generation of small-molecule inhibitors acting on mutated BRAF, including vemurafenib, which was the first FDA-approved BRAF inhibitor administered to advanced stage melanoma patients." (PMID 36309522, 2022). "Univariate and multivariate analyses for OS and PFS in BRAF Wild type advanced melanoma patients." (PMID 36016960, 2022). "Therefore, three BRAF inhibitors (vemurafenib, dabrafenib, and encorafenib) were approved for melanoma treatment." (PMID 36209184, 2022). "The aim of this study was to investigate whether the WNT5A downstream target MARCKS is an effective antimetastatic target in melanoma patients who have developed acquired resistance to BRAF inhibitors." (PMID 36551563, 2022). "Of these, one of the most represented PIK3CA mutations (affecting 4% of melanoma patients, according to COSMIC data) with a pathogenetic role in drug resistance is the PIK3CA H1047R mutation associated with both anti-BRAF and anti-MEK inhibitors of drug resistance." (PMID 35335966, 2022). "Although there was no direct evidence for the association between TYROBP and melanoma, given the important association between these hub genes and immune infiltration, we regard them as potential therapeutic targets for patients with BRAF mutations." (PMID 36531226, 2022). "Notably, 28% of patients with sun damage-related melanoma harbor KIT gene mutations, whereas 10% harbor BRAF mutations and 5% harbor NRAS mutations." (PMID 35356202, 2022). "On the other hand, although the association between BRAF/MEKi and GM in melanoma has not been described in previous studies, the role that both have in modulating the immune system demonstrates indirect signs of a possible correlation between them." (PMID 36233289, 2022). "In melanoma, acquired resistance to vemurafenib is a common result from MEK-ERK signaling reactivation achieved by diverse genetic mechanisms, including gain-of-function mutations in NRAS and KRAS, mutant BRAF amplification or MAP2K1 mutation." (PMID 35205704, 2022). "Thus, a combination of dabrafenib (BRAF inhibitor), trametinib (MEK inhibitor), and hydroxychloroquine (autophagy inhibitor) has been tested in patients with advanced melanoma bearing BRAF mutations." (PMID 36009363, 2022). "However, the second-generation MEK inhibitor binimetinib elicited similar rates of partial response, i.e. ∼20% in patients with NRAS- and BRAF-driven melanoma in a phase II clinical trial." (PMID 35234863, 2022). "NF1 loss often happens in melanomas lacking mutations in BRAF or NRAS, although in 4% of CM these three mutations can coexist." (PMID 36143375, 2022). "This retrospective study, including 135 metastatic melanoma patients who received consecutive treatments with BRAF/MEKi and CPI, or vice versa, provides evidence that front-line treatment with CPI is associated with favorable tumor control and overall survival in patients with BRAF-mutant melanoma." (PMID 35565212, 2022). "Therefore, we tested the effect of lj‐2‐66 on the level of ROS and found that lj‐2‐66 increased the production of ROS in numerous BRAF‐mutant melanoma cell lines." (PMID 35332658, 2022). "Following the discovery of BRAF mutations in cancers, including melanoma, it was found that benign Spitz nevi do not contain actually BRAF mutations, marking an important distinction of these tumors with other melanocytic lesions." (PMID 35747831, 2022). "Such examples include the prescription of vemurafenib to melanoma patients carrying the BRAF V600E or warfarin and clopidogrel (Plavix) drugs prescribed for cardiovascular disease-treatment, the response of which is affected by genetic polymorphisms (VKORC1, CYP2C9 and CYP2C19 genes)." (PMID 35260588, 2022). "Therefore, treatment regimens that inhibit BRAF signaling while preventing acquired resistance are also gaining importance in the field of molecularly targeted melanoma therapy." (PMID 35954441, 2022).